GALNT7 (polypeptide N-acetylgalactosaminyltransferase 7)
Diseases named in the same sentence as GALNT7 in open-access papers (continued):
Sharing a sentence is not in itself a finding about the gene and the disease.
tumor (continued). "On the contrary, in melanoma and hepatocellular carcinoma GALNT7 plays a tumor-restraining role." (PMID 36555445, 2022). "The research also reported that inhibiting GALNT7 expression might contribute to tumor regression following steroid androgen hormones depletion therapy." (PMID 32308562, 2020). "Moreover, overexpression of miR-125a-5p can neutralize the effect of GALNT7 on tumor proliferation and invasion." (PMID 32308562, 2020). "Moreover, in relation to the control and NC-mimic groups, the level of miR-125a-5p in tumor increased, while the protein expression of GALNT7 decreased in miR-125a-5p mimic group (P < 0.01)." (PMID 32308562, 2020). "Thus, we concluded that knockdown of GALNT7 played tumor-suppressive role on cell proliferation and invasion." (PMID 32308562, 2020). "GALNT7 displays a tumor-suppressor effect also in hepatocellular carcinoma cells." (PMID 28481247, 2017). "In vivo, GALNT7 knockdown reduced tumor growth, enhanced CD8+ T cell infiltration, and increased interferon gamma (IFN-γ) production within the tumor microenvironment." (PMID 42318657, 2026). "On the other hand, among the tumor-specific 63 ceRNAs, GALNT7, KLF9, and DAB2, which are common to all three tumor tissues and were significantly expressed in at least two tissues, were found in this core miRNA:ceRNA cluster." (PMID 38627780, 2024). "For CA12, GALNT7, LMO3, and SLC43A3 there is good separation in expression between tumor and normal tissue at each dose level as well as a suggestion of opposing trends with dose." (PMID 22848350, 2012). "GALNT7 IHC revealed granular cytoplasmic staining in nonneoplastic epithelial cells and tumor cells at variable levels, whereas no staining was observed in stromal or immune cells." (PMID 40824763, 2025). "In our study, GALNT7 expression was increased in metastatic CRC cells and tumor tissues." (PMID 29970122, 2018). "Most importantly, experimental studies do not consistently support the role of GALNT7 in the tumor." (PMID 34819077, 2021).
GALNT7 also shares sentences with these, for which no sentence is quoted: breast carcinoma (5 papers); benign prostate hyperplasia (2); nasopharyngeal carcinoma (2); adenocarcinoma (1); adenoma (1); brain tumor (1); diabetes (1); eosinophilia (1); esophageal squamous cell carcinoma (1); gall bladder cancer (1); gastrointestinal stromal tumor (1); glioblastoma (1); lung adenocarcinoma (1); multiple myeloma (1); nodular melanoma (1); non-small cell lung carcinoma (1); ovary carcinoma (1); pancreatic adenocarcinoma (1); pancreatic cancer (1); superficial spreading melanoma (1); type 2 diabetes mellitus (1).